RRM2 (ribonucleotide reductase regulatory subunit M2)
Diseases named in the same sentence as RRM2 in open-access papers (continued):
Sharing a sentence is not in itself a finding about the gene and the disease.
cancer (continued). "In addition, we found that AFAP1-AS1 participated in positively modulating luciferase activity of RRM2 3′ UTR and RRM2 level by acting as a sponge of miR-139-5p in cancer cells, suggesting that RRM2, as AFAP1-AS1, is a oncogenic regulator." (PMID 31696057, 2019). "This suggests that targeting ATR-mediated RRM2 phosphorylation may represent a potential new therapeutic strategy for cancer therapy." (PMID 31324785, 2019). "Our studies using acetyl-mimetic RRM2 mutants reveal that acetylation of RRM2 at K95 reduces the intracellular dNTPs pool and decreases DNA replication fork progression, leading to suppression of cancer cell growth in vitro and in vivo." (PMID 31324785, 2019). "Taken together, these findings suggest that RRM2 may act not only as an oncogene, but also as a promising prognostic biomarker and potential therapeutic target in cancer." (PMID 30898978, 2019). "Accumulating evidence has suggested that targeting RRM2 may be a novel strategy for cancer treatment." (PMID 30898978, 2019). "Besides, regarding with the relationship between anticancer drugs and hub genes, TOP2A and RRM2 were the targets of cancer drugs in patients with OC." (PMID 31729978, 2019). "These complex regulation mechanisms mediated by cyclin F could be significant to the cancer field, since aberrant expression of RRM2 has been found in multiple types of cancers and failure to maintain the balance of dNTP can cause genome instability." (PMID 31475738, 2019). "Since overexpression of RNR is one of the mechanisms underlying gemcitabine resistance in cancer cells, we attempted to study whether the combined treatment of afatinib and gemcitabine could affect the protein levels of RRM1 and RRM2." (PMID 29765556, 2018). "RRM1 and RRM2 are often overexpressed in cancer tissues including lung." (PMID 29765556, 2018). "However, different from those key genes with cancer/testis expression pattern, RRM2 shows ubiquitous expression among various organs." (PMID 30386706, 2018). "RRM2 is widely acknowledged as a pro-carcinogenic gene upregulated in several cancers." (PMID 30386706, 2018). "Moreover, some PCGs, such as IMPDH2, RRM2, and PAICS, involved in this subpathway region are closely associated with colorectal or other types of cancer." (PMID 28152521, 2017). "However, the abnormal expression level of RRM2 is a consequence of dysregulation in most cancer cells." (PMID 27801665, 2016). "Based on our previous work, we hypothesized that inducing autophagy would decrease RRM2 levels and sensitize cancer cells to COH29, a novel RR inhibitor." (PMID 26675256, 2016). "In a human study, expression of the Rrm2 gene was shown to be increased in various types of cancer." (PMID 27266874, 2016). "The sensitivity to the WEE1 inhibitor results through DNA replication stress because of RRM2 depletion, suggesting that other cancers exhibiting such replication stress may be targeted similarly." (PMID 26602815, 2015). "The RRM2 expression in the cancer tissues was higher than that in high-grade dysplasia (median H score: 1.0 vs. 0.5; Hommel's adjusted p<0.001), low-grade dysplasia (median H score: 1.0 vs. 0.5; Hommel's adjusted p = 0.002) or normal (median H score: 1.0 vs. 0.5; Hommel's adjusted p<0.001) tissues." (PMID 24637958, 2014). "Finally, we observed that the cervical patients receiving cisplatin-related treatment whose cancer tissues exhibited positive RRM2 immunoreactivity had a worse prognosis." (PMID 24637958, 2014). "Of 28 patients who had cancer tissues positive for RRM2, 14 had recurrence or expired." (PMID 24637958, 2014).
cancer (continued). "Knocking down RRM2 also sensitizes cancer cells to the cytotoxic effects of the nucleoside analogs." (PMID 25213022, 2014). "And there are also some studies explain why RRM1 and RRM2 play opposite roles in cancer outcomes." (PMID 23922955, 2013). "Therefore, RRM2 is also an important therapeutic target for DNA replication-dependent diseases such as cancer." (PMID 19250552, 2009). "We supposed that higher vascular density might partially contribute to growth advantage of RRM2-overexpressing cancer cells." (PMID 19250552, 2009). "We and others had reported that overexpression of human RRM2 could enhance the invasive and metastatic potential of various human cancer cells." (PMID 19250552, 2009). "To answer whether overexpression of RRM2 also effects on VEGF expression in cancer cells, we examined the levels of VEGF in the condition medium of KB cells." (PMID 19250552, 2009). "The findings indicated that RRM2 generally showed significantly high expression levels in most cancer types, especially in malignant tumors of epithelial origin, suggesting that it may play an important role in the development of these cancers." (PMID 41333212, 2025). "Furthermore, GSEA analyses indicated that patients with high levels of RRM2 exhibited enrichment in various biological processes and pathways, including cell cycle, p2 signaling pathway, DNA replication, small cell lung cancer, apoptosis, and cancer pathways." (PMID 38699434, 2024). "Therefore, in this study, we uncovered for the first time the role of RRM2 in 33 different cancers." (PMID 38635758, 2024). "Furthermore, RRM2 is considered a target gene of E2F transcription factor in certain cancers." (PMID 39437704, 2024). "Furthermore, noteworthy findings reveal that RRM2 inhibition can sensitize cancer cells to chemotherapy and radiation therapy, indicating that RRM2 inhibition may have potential utility as a combination therapy with existing cancer treatments." (PMID 37968699, 2023). "Our results imply that RRM2 might influence the efficacy of cancer immunotherapy." (PMID 35740608, 2022). "Besides, RRM2 had a good prediction accuracy of diagnosis (AUC > 0.90) in pan-cancer." (PMID 35740608, 2022). "Although there was some controversy regarding whether autophagy should be turned on or off to treat cancer, at least in this context, our data confirmed that RRM2 downregulation mediates the anti-proliferation effect of PECT on GBM, which depended on the increase of autophagic flux." (PMID 35651787, 2022). "High expression of RRM2 may lead to advanced pathologic stage across TCGA cancers." (PMID 35740608, 2022). "Notably, among the 22 immune cells, the correlation matrix portrayed that RRM2 expression had a negative association with CD8+ T cells in various cancers, including AA, BRCA, ESCA, LAML, PAAD, PRAD, SKCM and THCA." (PMID 35740608, 2022). "Growing evidence suggests that RRM2 may be a promising cancer therapeutic target." (PMID 35911380, 2022). "Moreover, intratumoral downregulation of RRM2 leads to the induction of apoptosis in cancer cells." (PMID 35456698, 2022). "Interestingly, RRM2 is generally highly expressed in cancers." (PMID 36678539, 2022). "Finally, immunohistochemistry (IHC) staining showed that the protein expressions of both MYBL2 and RRM2 were significantly upregulated in the cancer tissues compared to their paired normal tissues in our cohort of 69 CRC patients with a strong correlation coefficient between their expression levels." (PMID 34234118, 2021). "Additionally, RRM2 dysregulation is related to chemoresistance during cancer treatment." (PMID 33411689, 2020). "Knockdown of RRM2 by siRNA may potentially inhibit cancer angiogenesis." (PMID 31673243, 2019). "Since disruption of Sirt2 by siRNA or Sirt2 inhibitor AGK2 suppressed dNTP synthesis leading to cancer cell growth inhibition, pharmacological control of RRM2 acetylation by targeting its upstream deacetylase may represent a novel and effective approach for cancer therapy." (PMID 31324785, 2019).
cancer (continued). "Thus, the different co-expressed gene networks are compatible with the opposite roles and different underlying mechanisms of RRM2 and RRM2B in different types of cancers, which further stressed the importance of the rationale of the use of RR inhibitors in precision cancer medicine." (PMID 31637211, 2019). "Consequently, RRM2 has been proposed as biomarker for the prognoses of some cancer patients." (PMID 28507282, 2017). "Furthermore, our results in budding yeast suggest that telomerase-positive cancer cells may be more sensitive to RRM1/RRM2 inhibition than ALT-positive cancer cells." (PMID 29069086, 2017). "We hypothesized that RRM2 is correlated with the progression of cancer of uterine cervix." (PMID 24637958, 2014). "Knockdown of RRM2 by RNA interference such as siRNA may potentially inhibit cancer angiogenesis." (PMID 19250552, 2009). "This silencing resulted in the suppression of key prostate cancer subtype 1 (PCS1) genes, specifically FOXM1 and RRM2, ultimately contributing to an aggressive phenotype." (PMID 39972491, 2025). "The results showed a significant increase in RRM2 and GAPDH expression in the cancer cell lines compared to BEAS-2B (both P < 0.05)." (PMID 40341308, 2025). "The magnitude of differential expression of RRM2 and ADH1B in each cancer type was presented based on proteomic and transcriptomic data sourced from CPTAC as well as transcriptomic data from TCGA-GTEx." (PMID 39884577, 2025). "Ribonucleotide reductase regulatory subunit RRM2 is highly expressed, whereas alcohol dehydrogenase ADH1B is underexpressed across all 13 cancer types." (PMID 39884577, 2025). "For instance, YBX1 is an interactive partner of lincNMR that regulates the expression of downstream RRM2, TYMS and TK1 by binding to their promoters, governing nucleotide metabolism and cell proliferation in cancer." (PMID 38491348, 2024). "Furthermore, RRM2 may play an important role as a bridge between senescence and cancer development." (PMID 38804044, 2024). "Ribonucleotide reductase regulatory subunit M2 (RRM2), as an enzyme regulating deoxyribonucleotide production, has been realized to have contribution to a variety of cancers, including CC." (PMID 38341592, 2024). "Multiple types of cancer, including Ewing sarcoma tumors, are sensitive to RNR inhibitors or a reduction in the levels of either the RRM1 or RRM2 subunits of RNR." (PMID 37599787, 2023). "RRM2 is known to regulate DNA-damage response, cancer aggressiveness, and drug resistance, and recent studies have validated FOXM1 as a RRM2-directing transcription factor." (PMID 36597126, 2023). "Gemcitabine was shown to inactivate ribonucleotide reductase activity by interfering with RRM2 and binding to RRM1 by its diphosphate form, and therefore, has been approved for the treatment of various types of cancer including HCC." (PMID 36768940, 2023). "Impressively, TK1, RRM2 and IMPDH1 were positively correlated with Myc/Myc signatures in multiple cancer types, whereas HSD17B6, PYGM and ACACB were negatively correlated with Myc/Myc signatures." (PMID 36629054, 2023). "It has also been shown that in cancer cells the small subunit of RNR, RRM2, is degraded by the proteasome in a cell cycle-dependent manner." (PMID 36983519, 2023). "Immunohistochemical staining of RRM2 protein in HCC and normal liver tissues showed that 2 out of 10 HCC cases (20%) had high/medium RRM2 staining, which was the highest among 20 other cancer types." (PMID 36768940, 2023). "RNR is an antineoplastic target that manifests therapeutic benefits in many types of cancers, and its catalytic activity requires both RRM1 and RRM2 homodimers." (PMID 35546402, 2022). "We downloaded the TCGA mRNA sequencing and clinical data of 33 cancer types from the UCSC Xena platform and used the Cox proportional hazards model to examine the prognostic assessment value of RRM2 in pan-cancer." (PMID 36518297, 2022).
cancer (continued). "Studies have shown that the overexpression of RRM2 and KIF20A usually accompanies the occurrence of cancer and plays a malignant role in cancer." (PMID 34787756, 2022). "For instance, a RRM2 inhibitor, COH29, can inhibits the growth of gemcitabine resistant cancer cells." (PMID 35911380, 2022). "Ribonucleotide Reductase Regulatory Subunit M2 (RRM2) has been reported as a therapeutic target via activating EMT in HNSCC and other cancers." (PMID 35546399, 2022). "Subsequently, we disclosed that RRM2 expression was also correlated with TMB, MSI, NEO and CTL in most cancers, predicting the benefits of immunotherapy." (PMID 35740608, 2022). "Since epithelial–mesenchymal transition (EMT) is an important contributor to cancer cell migration, we next performed Western blot to assess the expression of EMT markers upon RRM2 silencing." (PMID 34895038, 2021). "A lot of target genes of miR-140-3p, including RRM2, PD-L1, MAPK and BRD9, can be remarkably suppressed by miR-140-3p in cancer cells through binding to the 3′-untranslated regions (3′ UTRs)." (PMID 34496800, 2021). "At the same time, the safety and efficacy of other types of RRM2 and VEGF biological or small molecule inhibitors have been extensively studied in clinics, either alone or in combination with other anti-cancer agents, presenting adequate response rates." (PMID 34683911, 2021). "In the present study, VEGFA, RRM2, H2AFX, CHEK1, CEP55, CDCA8 and AURKA were significantly upregulated; however, VCL, TPM2 and TPM1 were significantly downregulated in cancer samples of BC." (PMID 34112125, 2021). "Since no significant expression changes of TAF15 existed between the cancer and normal tissues of CRC, probably MYBL2 dominated the S-phase RRM2 transcription in the complex in CRC cells." (PMID 34234118, 2021). "For example, upregulation of CEMIP, RRM2, LAMC2, SCD, TNS4, and PLAU in humans is prognostically unfavorable for various cancers; these genes have CR-upregulated mouse orthologs." (PMID 34202278, 2021). "Of the 10 proteins, the preceding text showed that some studies identified RRM2, PLOD2, MKI67, MCM5, and CKD1 promoted cancer progression and FBP1, FBP2, ENO3, GPD1, and ASS1 inhibited cancer progression, which was consistent with our results." (PMID 33200655, 2020). "In total, 32 cancer related genes including CCND1, MKI67, HIF1A, CDH1, RRM2, and FOXM1 were subsequently identified through Ingenuity Pathway Analysis." (PMID 32348423, 2020). "Among the cancer driver genes that experienced epigenetic changes in at least five cancer types, we identified eight genes: CEP55, PIF1, RRM2, NCAPH, ZEB2, CIT, FLI1, and PCDH17." (PMID 31900418, 2020). "To further confirm the ability of sorafenib to downregulate RRM2 mRNA, we mined their relationship in an NCI-60 cancer cell panel via the NCI Transcriptional Pharmacodynamics Workbench." (PMID 31936661, 2020). "We detected the expression of the other six genes (MCM3, SPATS2, RRM2, NT5DC2, LRRC1, and RNASEH2A) in 30 pairs of HCC and para-carcinoma tissue by immunohistochemical staining assays." (PMID 32213663, 2020). "In contrast, RRM1, RRM2, and RRM2B were ranked in the top 10% of the down-regulated DEGs in only 8.4% (30 of 358), 4.5% (16 of 355), and 4.8% (10 of 209) of the cancer studies, respectively." (PMID 31637211, 2019). "For example, they are inhibited by gemcitabine (RRM2), marimastat (MMP9 and MMP11) for treating several cancers." (PMID 30729033, 2019). "We found that the mRNA expression levels of RRM1, RRM2, and RRM2B ranked in the top 10% of the up-regulated DEGs in 24.0% (86 of 358), 38.3% (136 of 355), and 10.5% (22 of 209) of the identified cancer studies, respectively." (PMID 31637211, 2019). "Target gene candidates in cancer therapy are mainly involved in oncogenes, angiogenesis and proliferation, like PLK1, EphA2, RRM2, KRAS, PKN3 and VEGF, which have been tested as target genes in early-phase clinical trials for RNAi-based cancer therapies." (PMID 30065155, 2018).
cancer (continued). "For example, starvation- or rapamycin-induced autophagy had been shown to decrease RRM2 level and accompanied by a decrease in RNR activity and dNTP pools in human cancer cells." (PMID 26675256, 2016). "We propose that autophagic degradation of a RRM2, the target of COH29, promotes cell death, whereas in other contexts autophagy can protect cancer cells from death." (PMID 26675256, 2016). "Above results verified a positive correlationship between CREB1 and RRM2 in clinical CRC specimens, which is involved in cancer progression and indicates a poor prognosis for CRC patients." (PMID 27801665, 2016). "The goal, therefore, is to discover truly selective RRM1 or RRM2 compounds for use as monotherapy and in combination with CHK1 inhibitors or chemotherapy for the treatment of cancer." (PMID 25375241, 2014). "Three types of cancers are covered by 22 2-gene combinations, with MMP11+RRM2 and MMP7+MMP9 representing the top 2-gene markers with at least 75% classification accuracy." (PMID 21060876, 2010). "Genes that were upregulated by demethylation but not methylated included genes that have been described previously as TSGs in other cancer types (e.g. BAP1, IGSF4, RRM2 (Gautam and Bepler (2006)), PMAIP1, claudin-1; and ICAM1;)." (PMID 18195710, 2008). "Next, the prognostic value of RRM2 and ADH1B was also explored in cancer." (PMID 39884577, 2025). "Remarkably, the oncogenes shown are Known to decrease apoptosis that could result in cancer cell survival like YBX1, SNRPE, RRM2, and COX6B1." (PMID 41347211, 2025). "The up-regulated expression of RNR in cells is characteristic of many cancers, and an investigation of RNR gene expression in human cancers using the ONCOMINE database showed that RRM2 was ranked in the top 10% of the most overexpressed genes in 73 out of the 168 cancers analyzed." (PMID 40048445, 2025). "Further correlation analysis, pan-cancer analysis (using TCGA and GTEx data), and detailed analysis across pathological types and TNM stages were performed to identify and characterize key molecules, such as RRM2." (PMID 41333212, 2025). "The results indicated that the expression levels of MYBL2 and RRM2 were significantly higher in cancer tissues compared to adjacent non-cancerous tissues." (PMID 40885709, 2025). "Altogether, RRM2, CCNB1, HMMR, and EZH2 seemed to be key genes in cancer development." (PMID 39118438, 2024). "Although the oncogenic role of RRM2 has been elucidated in several tumors, there is no pan-cancer evidence regarding the relationship between RRM2 and various cancer types based on big clinical data." (PMID 38635758, 2024). "RRM2 and TK1 had remarkably increased expression levels in several cancers." (PMID 37999212, 2023). "In most cancers, the mRNA expression of RRM1, RRM2, and RRM2B was generally increased." (PMID 36713030, 2023). "We found that RRM2 expression was significantly negatively correlated with neutrophils, CD8 T cells, DCs, and cytotoxic cells, and that immune cells play a crucial role in cancer immunology." (PMID 37056349, 2023). "RRM2 was reported as a key mediator of AKT-induced resistance to tamoxifen and chemical inhibition of RRM2 by Didox reversed tamoxifen-resistant phenotype such as cancer growth, migration and invasion." (PMID 36997866, 2023). "Furthermore, Cox regression analyses and KM survival curves demonstrated that RRM2 predicted poor OS and DSS in most cancers with TCGA and GEO." (PMID 35740608, 2022).